PBRM1 (polybromo 1)
Diseases named in the same sentence as PBRM1 in open-access papers (continued):
Sharing a sentence is not in itself a finding about the gene and the disease.
tumor (continued). "Alternatively, we found that PBRM1 mutations showed strong correlation with TMB, immune response and tumor immune microenvironment." (PMID 36699446, 2022). "A therapeutic experiment was only carried out in the PBRM1-mutated CD39 PDX, considering a very slow tumor growth in the others (more than 6 months)." (PMID 35326637, 2022). "ARID1A and PBRM1 encode a subunit of the SWI/SNF complex, and were mostly mutated in CCA, including association with tumor progression." (PMID 34070951, 2021). "Consistent with previous reports, the classical driver mutations associated with ccRCC, including alterations in VHL, PBRM1, BAP1, and SETD2, were identified in tumor samples." (PMID 33806963, 2021). "PBRM1 encodes a subunit of the SWI/SNF chromatin remodeling complex and has been implicated as a tumor suppressor gene in a wide range of other cancers." (PMID 34272401, 2021). "To explore the role and commonality of PBRM1 on tumor cells, we analyzed the genetic alternation frequency of PBRM1 in various tumors using bioinformatic methods." (PMID 34447697, 2021). "Overall, the frequency distribution of somatic mutations detected in our cohort is comparable to large-scale studies of primary tumours with VHL (40.5%), PBRM1 (40.5%), and KDM5C (32.9%) being the most frequently mutated genes in our cohort." (PMID 34944839, 2021). "The results showed that PBRM1 protein level is lower expressed in tumor tissues than in normal tissues only in ccRCC." (PMID 34447697, 2021). "The effects of PBRM1 deletion on tumor cells have been studied in human ccRCC tumor cell lines, but these experiments were in vitro and detached from the tumor microenvironment in vivo." (PMID 34447697, 2021). "Seven of the 64 tumour suppressors (ACVR2A, CSMD3, EPS15, MAP2K4, NF1, PBRM1 and RB1) had intronic mis-splicing mutations in multiple tissues." (PMID 33420369, 2021). "We also showed that the PBRM1 expression level combined with tumor stage can more accurately reflect the survival rate." (PMID 34447697, 2021). "In our research, we used the Renca subcutaneous model to investigate the effects of PBRM1 in the ccRCC tumor microenvironment." (PMID 34447697, 2021). "Previous studies have suggested that PBRM1 knockdown promotes proliferation and invasion of ccRCC tumor cells." (PMID 34535962, 2021). "In PBRM1 wild-type tumors, IFNγ induces the tumor cell-autonomous expression of STAT1, IRF1 and of chemoattractive chemokines, which enhances T-cell infiltration and activation." (PMID 32358509, 2020). "In pRCC2 tumors, we observed a SMARCB1 driver mutation in one pRCC2; TERT promoter in two pRCC2; SETD2, PBRM1 and NF2 in one pRCC2 tumor each." (PMID 32555180, 2020). "Our Renca subcutaneous tumor model confirmed that PBRM1 inactivation slowed tumor progression, while Pbrm1 knockout tumors were more resistant to early treatment with PD-1 antibody." (PMID 32358509, 2020). "Taken together, these findings demonstrate that PBRM1 is a key regulator of tumor cell-autonomous immune response in RCC, and loss of PBRM1 function likely contributes to the blunted ICB response experienced by many patients." (PMID 32358509, 2020). "Frozen tumor tissues and plasma were used to measure PBRM1, BAP1, SET domain-containing 2 (SETD2), KDM5C, FOXC2, CLIP4, AQP1, DDX11, BAIAP2L1, and TMEM38B mRNA levels, and correlation with the Fuhrman grade was investigated." (PMID 32392781, 2020). "In untreated cohorts, Renca control knockout tumors grew quickly and all mice were sacrificed within 20 days after tumor inoculation due to tumor growth; however, Pbrm1 knockout tumors grew significantly slower and survived longer." (PMID 32358509, 2020).
tumor (continued). "In one of these subclasses, we found frequent BAP1 (n = 22) and PBRM1 (n = 16) alterations—including 5 cases with BAP1 and PBRM1 aberrations in the same tumor (total n = 33 tumors)." (PMID 33087175, 2020). "Next, we performed tube formation matrigel assay to determine the effects of PBRM1-knockdown in ccRCC cells on tumor angiogenesis." (PMID 33177244, 2020). "By analysing the expression of five subunits of the SWI/SNF complex (INI1/SMARCB1, SMARCA2, SMARCA4, ARID1A, PBRM1), we further explored the relevance of alterations in chromatin remodelling in glandular differentiated tumours." (PMID 32198650, 2020). "When comparing the changes with or without treatment, anti-PD-1 treatment provided more significant survival benefit and tumor growth control in mice bearing control knockout tumors than in those with Pbrm1 knockout tumors." (PMID 32358509, 2020). "Univariate and multivariate analyses revealed that tumor size (Hazard ratio = 2.47, p = 0.04) and PBRM1 (Hazard ratio = 28.69, p = 0.05) were related to metastasis in clear cell RCC." (PMID 32811483, 2020). "This analysis suggests that the link between PBRM1 and p21 observed in cell lines is conserved in human tumor samples." (PMID 31863007, 2019). "(2018) used in vitro growth curves of Caki‐2 or RCC4 cells re‐expressing wild‐type or BD mutants as a gauge of PBRM1's tumor suppressor function." (PMID 30585695, 2019). "In in vitro models in which both transcription factors are expressed, PBRM1 showed tumor suppressive activity." (PMID 31861590, 2019). "This is likely caused by many genetic and epigenetic changes that occur at higher grades or tumor stages that disrupt the correlation between PBRM1 and p21 expression." (PMID 31863007, 2019). "In this context, multiregion sequencing-based studies have highlighted the potential relevance of PBRM1 alterations for tumor growth and metastatic capacity, which are determinant for clinical outcome." (PMID 31861590, 2019). "The inactivation of BAP1 and PBRM1 mainly contribute to different pathways of tumor evolution, being almost mutually exclusive events conferring different prognosis." (PMID 31861590, 2019). "The mutation of the remaining allele of PBRM1 or BAP1 would lead to tumorigenesis, and depending on which gene is mutated, to different tumor aggressiveness." (PMID 31861590, 2019). "Patients with high expression of PBRM1 in the tumor had a significantly worse OS than those with low PBRM1 expression." (PMID 31861590, 2019). "They tried to correlate the tumor genome profile with the clinical benefit from anti-PD1 therapy and discovered there was a correlation between PBRM1 mutations and clinical benefit." (PMID 31861590, 2019). "These included mutations in the well-known ccRCC-specific cancer driver genes VHL and PBRM1, which were, therefore, most likely involved in the initiation of tumour development in this patient." (PMID 31212796, 2019). "Epigenetic regulators such as PBRM1 and BAP1 – which act as tumor suppressors – are frequently mutated and associated with distinct clinical outcomes in ccRCC patients." (PMID 30814637, 2019). "Although these mutations failed to significantly change PBRM1's binding to chromatin, they significantly impaired PBRM1's ability to bind to promoters and regulate gene expression and severely crippled PBRM1's tumor suppressor function." (PMID 30585695, 2019). "So our findings suggest that PBRM1's molecular and tumor suppressor functions depend on the recognition of H3K14ac by multiple BDs, and PBRM1 is an important reader of H3K14ac, a universal epigenetic marker of actively transcribing genes." (PMID 30585695, 2019).
tumor (continued). "In a nude mouse xenograft model, restoration of wild-type PBRM1 in Ren-01 PBRM1 KO cells suppressed tumor growth when compared with cells expressing either GFP or the BD4* PBRM1 mutant." (PMID 31863007, 2019). "More recently, another study showed that depressed PBRM1 and VHL expression was associated with elevated tumor aggressiveness." (PMID 30349421, 2018). "Its inhibitory effect on tumor growth can be relieved by the loss of PBRM1, KDM5C, SETD2 or BAP1 to promote robust tumor growth." (PMID 30355451, 2018). "Results identified two known mutations in the tumor biospecimen: BAP1 splice site 1729 + 1 G > A and PBRM1 N258fs*6." (PMID 29440675, 2018). "Second, genetic testing of the tumor cells from subject 1 identified two mutations specific to the studied tumor: BAP1 splice site 1729 + 1 G > A and PBRM1 N258fs*6." (PMID 29440675, 2018). "As with VHL, PBRM1 and SETD2, biallelic inactivation of BAP1 via mutation and loss of heterozygosity fit a two-hit tumor suppressor profile." (PMID 30355451, 2018). "Tumor #7 from the stage 1 group provided an example: the SMARCA2 loss was a truncal event, PBRM1 loss was a branch event, while ARID1A and SMARCA4 losses were branch events that happened even later." (PMID 28445125, 2017). "Herein, we observed minimal intra- and inter-tumor heterogeneity of BAP1 and PBRM1 loss of expression in metastatic ccRCC tumors." (PMID 28327121, 2017). "The Vhl−/−;Pbrm1−/− tumours displayed solid growth patterns with prominent vasculature and were composed of cells with eosinophilic or clear cytoplasm, and increased proliferative index, features reminiscent of the histopathological appearances of human ccRCC." (PMID 29229903, 2017). "We found limited genetic concordance between primary and secondary tumor sites with private mutations in FLT4, MTOR, ITGA5, SETD2, PBRM1, and BRCA1 on progression." (PMID 29088767, 2017). "The other patient with a PBRM1 mutation (RMH004) had a mutation in three of the five biopsies from the primary tumor and a different PBRM1 mutation in a tumor thrombus from the renal vein." (PMID 28327121, 2017). "Unlike other cancer types that are found to have recurrent mutations in oncogenes, ccRCC tumors are mainly associated with somatic mutations in tumor suppressor genes such as VHL, PBRM1, BAP1 and SETD2." (PMID 27556922, 2016). "To overcome these obstacles, we report the development of isogenic ccRCC cell lines that permit dissecting the transcriptional role of PBRM1 in tumor suppression." (PMID 27100670, 2016). "Our results provide some important insights into the PBRM1 regulation in the tumor development of ccRCC." (PMID 27556922, 2016). "The decrease in cellular proliferation upon PBRM1 re-expression was confirmed, validating the functional role of PBRM1 as a tumor suppressor in a cell-based model." (PMID 27100670, 2016). "Compared with NC-transfected UM-UC-3 cells, si-PBRM1-transfected cells led to an increased size of tumor volume (p < 0.05)." (PMID 25978027, 2015). "The mechanism of PBRM1 in tumor suppression is poorly understood despite extensive studies in recent years." (PMID 25978027, 2015). "We and others have reported the associations of PBRM1, SETD2, BAP1, and KDM5C mutations with advanced stage, grade, and tumor invasiveness, and discovered that SETD2 and BAP1 mutations are associated with lower cancer-specific survival rates." (PMID 25124064, 2014). "Based on our cohort (n = 14), we estimate that among patients harboring a mutation in PBRM1, SETD2, BAP1, or KDM5C, the mutation would be present in 75%, 70%, 58%, and 55% of the tumor, respectively." (PMID 25124064, 2014). "In comparison with the PBRM1 mutation, BAP1-deficient tumours were of higher grade and had distinct gene expression profiles." (PMID 23016578, 2012). "We hypothesized that vimentin inhibition would reverse the high tumor-grade phenotype and decrease metastasis of Pbrm1-null PDAC in mice." (PMID 40454484, 2025).
tumor (continued). "Therefore, PBRM1 is a critical determinant of tumor grade, EMT, and metastasis in PDAC and functions by directly regulating vimentin expression." (PMID 40454484, 2025). "Notably, the tumor growth rate was markedly suppressed by the PBRM1 overexpression plasmid‐loaded nanomedicine, while it was significantly accelerated by the shPBRM1 plasmid‐loaded nanomedicine." (PMID 39823528, 2025). "In the genomic analysis of the primary tumor tissue of the TRACERx Renal study, the multi-region sequencing underscores intratumoral heterogeneity and validates clonal mutual exclusivity patterns associated with BAP1 and PBRM1/SETD2." (PMID 41440218, 2025). "However, PBRM1 is known to promote resistance to T-cell-dependent killing in preclinical cancer models, hence the possibility of affecting the anti-tumor immune response." (PMID 41278204, 2025). "In addition, we synthesized a peptide to promote the degradation of PBRM1 by enhancing the interaction between PBRM1 and p62, providing a promising tumor therapeutic approach with PBRM1 inhibition and PD‐1 blockade." (PMID 39656940, 2025). "Tumor recurrence and grade were significantly correlated with PBRM1 expression." (PMID 40454484, 2025). "Moreover, U0126 notably impeded the migration and invasion of HuCCT1‐shPBRM1 cells, indicating that PBRM1 exerts an anti‐tumor effect through ERK1/2 pathway inhibition, a process blocked by an extracellular signal‐regulated kinase 1/2 (ERK1/2) inhibitor." (PMID 39823528, 2025). "In conventional ccRCC, the loss of chromosome 3p is a common early event, frequently leading to the simultaneous inactivation of key tumor suppressor genes, including PBRM1, BAP1, and SETD2, all of which are involved in chromatin remodeling and histone regulation." (PMID 40940841, 2025). "Tumor mutation burden (TMB) analysis revealed that the high-risk group exhibited significantly higher mutation frequencies compared to the low-risk group, particularly in key driver genes such as VHL and PBRM1." (PMID 40909272, 2025). "However, the overall mutational landscape—including tumor mutational burden (TMB) and recurrent alterations in key genes like ARID1A and PBRM1—was largely overlapping between groups." (PMID 39941902, 2025). "Consistently, silencing PBRM1 significantly increased CD8+ tumor‐infiltrating T lymphocytes (TILs), which could be reversed by clearance of macrophages." (PMID 39656940, 2025). "However, the tumor volume and the number of hepatic metastatic foci in the PBRM1 mutant group were significantly reduced after administering the PD-1 antibody." (PMID 40093909, 2025). "For example, PBRM1, which we found in CCRCC, is a subunit of the PBAF chromatin remodeling complex thought to be a tumor suppressor gene whose mutations may confer synthetic lethality to DNA repair inhibitors." (PMID 39775839, 2025). "Therefore, PBRM1 is a critical determinant of tumor grade not only before PDAC development but also after PDAC formation, and PBRM1 plays a tumor-suppressive role in PDAC progression." (PMID 40454484, 2025). "A hydrodynamic tail vein injection model with C57BL/6 mice was utilized to investigate whether PBRM1 can impede the tumor progression of iCCA cells in vivo." (PMID 39823528, 2025). "Therefore, we performed ATAC-sequence to directly assess chromatin accessibility in Pbrm1 deficient and control HCT116 tumor cells." (PMID 40093909, 2025). "In addition, TCGA data analysis revealed that PDAC with PBRM1 deletion was significantly correlated with a worse tumor grade and an aggressive squamous molecular subtype." (PMID 40454484, 2025).
tumor (continued). "Univariate Cox proportional hazards analysis revealed that several parameters, including tumor grade, expression level of PBRM1, tumor recurrence, residual tumor, N category, and lymphatic invasion were significant predictors of overall survival in patients with PDAC." (PMID 40454484, 2025). "In addition, the transcription levels of the markers of M1 macrophages, TNFα, IL12, and IL1b, were significantly upregulated after co‐culturing with PBRM1 knockdown tumor cell culture medium." (PMID 39656940, 2025). "Next, we hypothesised that the induction of E27 exclusion in PBRM1 enhances immune cell-mediated tumour-killing activity, leading to tumour suppression." (PMID 39375538, 2024). "Since LF2 along with LF1 and LF5 levels were associated with patient overall survival, we generated Cox Proportional-Hazards models to evaluate how they compared to existing models of patient prognosis based on tumour stage, grade and somatic mutations (BAP1, SETD2, and PBRM1) (Table EV8)." (PMID 39592856, 2024). "In summary, our findings revealed that patients with POL&PBRM1 co-mutations exhibited significantly higher TMB, higher immunotherapy response signature scores, and more active anti-tumor immunity, suggesting a potentially favorable response to immunotherapy in these patients." (PMID 39218995, 2024). "Tumor suppressor activity of PBRM1; enhancement of tumor growth upon dysregulation." (PMID 39456765, 2024). "In addition, PBRM1 also affects the anti-tumor immune response, especially in preclinical cancer models by mediating resistance to T-cell-dependent killing." (PMID 38365747, 2024). "Third, the absence of tumor-specific genes, such as the relative absence of PBRM1 mutations in highly CD8+ T cells RCC, which was often associated with a better prognosis." (PMID 38291496, 2024). "In addition, mutations in the tumour suppressors BAP1, PBRM1 and SETD2, which co-localise with VHL on chromosome 3p and are frequently disrupted in ccRCC, suppress ISGF3-mediated ISG expression." (PMID 39282259, 2024). "Compared with normal tissues, the expression of CNV-amplified HA regulators was significantly increased in tumor tissues (e.g. HDAC3 in KIRC), while the expression of CNV-deficient HA regulators was significantly decreased (e.g. KAT2B, HDAC11 and PBRM1 in KIRC)." (PMID 37553641, 2023). "Our results indicate that this model (BPS-TA) induces low numbers of somatic mutations in Bap1 and Pbrm1 (but not in Setd2), known tumor suppressor genes in human ccRCC." (PMID 37217526, 2023). "Exposure to PARP inhibitors in the presence of a PBRM1 defect further promotes the replication stress, contributing to the accumulation of DNA damage and formation of micronuclei, which leads to the lethality of tumor cells." (PMID 37175555, 2023). "In this cohort of patients, conventional genomic markers including tumor mutation burden and neoantigen load failed to predict nivolumab response, while the PBRM1 truncated mutation was associated with longer patients OS and PFS." (PMID 36239411, 2023). "We also analyzed DACRs for PBRM1 mutants (9 tumors, not including 2 with both BAP1 and PBRM1 mutations) versus tumors without PBRM1 or BAP1 mutations (again using only tumor cells)." (PMID 36973268, 2023). "We observed various responses to palbociclib concerning both models (CD3, CD7) harboring a loss of CDKN2A/2B, and no tumor efficacy in the non-CDKN2A/2B-deleted PBRM1-mutated PDX (CD39)." (PMID 36505864, 2022). "Additional driver mutations in PBRM1, SETD2, and BAP1 may occur, and the number of driver events is significantly associated with tumor stage, grade, and presence of necrosis." (PMID 35463327, 2022). "Recently, PBRM1-defecient tumor cells were shown to be sensitized to PARP1 inhibitor." (PMID 35719970, 2022). "This indicates that there may be a balance between carcinogenesis and tumor suppressor immune activity of PBRM1 abnormalities, thereby affecting the overall biological behavior and prognosis of tumors." (PMID 35928964, 2022).